GHR (growth hormone receptor)
Diseases named in the same sentence as GHR in open-access papers (continued):
Sharing a sentence is not in itself a finding about the gene and the disease.
Hepatic steatosis (continued). "For example, when GHR is deleted in liver, hepatic steatosis is limited to males, xenobiotic metabolizing enzyme mRNAs are oppositely regulated in males compared to females, and apoptosis-related mRNA's are decreased in female brain and kidneys but not in males." (PMID 26233957, 2015). "However, the deletion of the hepatic GHR gene in mice also resulted in hepatic steatosis because of enhanced lipogenesis and reduced TG secretion from the liver." (PMID 24281711, 2012). "While the reduced levels of circulating growth hormone (GH) and insulin-like growth factor 1 (IGF-1) have been consistently observed in patients with hepatic steatosis, the molecular role of hepatic growth hormone receptor (GHR) in MAFLD pathogenesis remains unclear." (PMID 41847434, 2025). "Functionally, on the one hand, disruption of the GHR gene (Ghr gene) in the liver is characterized by lack of improved insulin sensitivity and severe hepatic steatosis 9; on the other hand, GHR deficiency protects against age‐related NLRP3 inflammasome activation and immune senescence." (PMID 31725956, 2020). "In mice, the liver-specific ablation of the GH receptor (GHR) increases lipid uptake and DNL, resulting in hepatic steatosis that cannot be reverted by IGF-1 treatment." (PMID 33071979, 2020). "Rescue of GH signaling via adeno-viral restitution of the GHR in liver, or STAT5 signaling in cells may reverse or prevent hepatic steatosis." (PMID 25566190, 2014). "Liver-specific abrogation of both GHR and STAT5 results in hepatic steatosis." (PMID 25566190, 2014). "Despite normal plasma FFA and minimal adiposity, the absent GHR activation could lead to hepatic steatosis because the activated STAT5 prevents this pathology." (PMID 24281711, 2012).
hepatocellular carcinoma (14 papers, 2011 to 2023). A malignant tumor that arises from hepatocytes. "Primary rat hepatocytes and human hepatoma cells, HuH-7, were used to study the dose and time-dependent kinetics of direct GHR activation by GH and somapacitan." (PMID 32053994, 2020). "In this study we have investigated the downstream receptor signaling in primary rat hepatocytes and human hepatoma cells together with the binding affinity for binding to the GHR of the long-acting GH derivative, somapacitan." (PMID 32053994, 2020). "In vitro, the human hepatoma cell line HuH7 also respond to insulin (10 nM) by up-regulation of GHR, although the study focused on concentrations of insulin superseding physiological levels." (PMID 28486400, 2017). "A synergistic additive effect of TNF-α and IL-1β on repressing GHR expression has been shown in Huh-7 human hepatoma cells." (PMID 28486400, 2017). "It haspreviously been reported that prolonged (8–24 h) but not short-term(4 h) insulin pretreatment inhibits GH signaling via the GHR/JAK2/STAT5Bpathway in rat hepatoma cells." (PMID 21559284, 2011). "However, a liver specific knockdown of GHR at 6 months was moderately protective against induced hepatocellular carcinoma." (PMID 37881503, 2023). "The aim of this study was to evaluate the hepatic expression of GHR/STAT5/IGF-1 signaling pathway in hepatocellular carcinoma (HCC) patients and to correlate the results with the clinico-pathological features and disease outcome." (PMID 36374927, 2022). "Study found that the expression of GHR and CDKN1A, one of the key inhibitors of cell cycle, were significantly down-regulated in hepatocellular carcinoma." (PMID 37322434, 2023). "Hepatocellular carcinoma (HCC) expresses higher levels of GHR than normal liver hepatocytes." (PMID 35865483, 2022). "Relationship between hepatic expression of GHR/STAT5/IGF-1 signaling pathway and clinico-pathological features of the tumor in cirrhotic patients with hepatocellular carcinoma." (PMID 36374927, 2022). "In liver cells or hepatoma cell lines (e.g., Huh-7 cells), TNFα and IL-1β induced by LPS only have minor effects on SOCS expression and their effects on GH resistance are mediated by reducing GHR gene transcription, probably through inhibition of Sp1/3 binding to GHR promoter." (PMID 32082258, 2020).
Hyperinsulinemia (13 papers, 2012 to 2025). An increased concentration of insulin in the blood. "Hyperinsulinemia also stimulates the expression of growth hormone receptor (GHR) in liver to possibly increase liver IGF-1 production by enhanced GHR signalling there." (PMID 26030767, 2015). "Although all the underlying mechanisms need to be clarified, it has been suggested that hyperinsulinemia upregulates growth hormone receptor (GHR) expression and thereby upregulates hepatic IGF-I production." (PMID 25566194, 2014). "In hyperinsulinemia, the growth hormone receptor (GHR) is upregulated by the increase of insulin concentrations in portal circulation thus increasing GHR signalling and hepatic IGF-I synthesis." (PMID 24073332, 2013). "Dysregulation of insulin, such as in the presence of hyperinsulinemia, may lead to the upregulation of the growth hormone receptor (GHR), consequently increasing hepatic production of IGF-I." (PMID 40431387, 2025). "Furthermore, hyperinsulinemia stimulates an increase of IGF-1 level through hepatic activation of growth hormone receptor (GHR), resulting in increased secretion of growth hormone (GH) which stimulates IGF-1." (PMID 33920079, 2021). "In a hyperinsulinemia state, elevated insulin levels lead to increased production of IGF-1 due to upregulated growth hormone receptor (GHR) signaling." (PMID 39410536, 2024). "Hyperinsulinemia is also known to increase circulating IGF1 production, either by up-regulating growth hormone receptor levels or by suppressing IGF binding protein (IGFBP) -1 and -2." (PMID 22226054, 2012).
steatosis (13 papers, 2011 to 2025). Increased lipid within the cytoplasm of cells. "The data set generated in this study is an interesting resource for meta-analyses with human and murine data sets that aim, for example, to investigate why GHR-deficient humans and rodents develop steatosis while pigs don't." (PMID 32277923, 2020). "The important role of the reciprocal shift in IGF1/GH and subsequent GH-mediated WAT lipolysis to the development of steatosis in these model systems is based on studies in mice with the loss of hepatocyte GHR signaling, due to the congenital liver-specific knockout of JAK2 (JAK2L)." (PMID 34685512, 2021). "GH also regulates adult metabolism to protect against the development of steatosis, which is via hepatic GHR signaling." (PMID 41154721, 2025). "Stratifying by BMI revealed 8/2367 DEP associated with steatosis in lean- and 12/2367 DEP in overweight/obese individuals, with two shared DEP (IGSF9 and GHR)." (PMID 39426127, 2024). "A recent study has identified a hepatocyte-specific role in growth hormone receptor (GHR) signalling in the regulation of steatosis." (PMID 39902162, 2024). "GHR expression levels were comparable in patients with simple steatosis and NASH (GHR/GAPDH cDNA ratio: 3.94 ± 1.82 in simple steatosis vs 3.53 ± 1.42 in NASH)." (PMID 30206761, 2018). "In line with these clinical findings, mice that express a GHR antagonist develop steatosis." (PMID 34685512, 2021). "Steatosis in humans has been associated with low circulating GH levels and IGF1 levels, as well as inactivating mutations in the GHR." (PMID 34685512, 2021). "While hepatic GHR mRNA expression levels were similar, IGF-mRNA expression was significantly reduced in patients with NASH when compared to obese females with simple steatosis." (PMID 30206761, 2018). "In humans, GHR and IGF-1 levels were determined in liver samples of 29 obese patients with non-alcoholic steatohepatitis (NASH) or simple steatosis." (PMID 30206761, 2018). "In a protein–protein interaction network, IGSF9 was found to have a central position, being correlated to FGF21, CES1, MAMDC4, and afamin (AFM) in PLHIV with steatosis, and to AFM and GHR in those without steatosis." (PMID 39426127, 2024). "Like serum levels, hepatic IGF-1 mRNA levels also decline with increasing degrees of steatosis, steatohepatitis, and fibrosis in adults, whereas IGF-1R and GHR expression does not appear to change with increasing severity of NAFLD." (PMID 37520312, 2023). "In addition, it has been suggested that GH may play a direct role in hepatic DNL since IGF-1 administration in GHR knock-down mice showed no improvement in TG levels, DNL, or steatosis." (PMID 36831184, 2023). "In their model of liver-specific GHR deletion, Fan and colleagues demonstrate that rescue of GHR expression reverses the liver phenotype, whereas infusion of IGF-1, which lowers serum GH to normal but does not restore hepatic GH signaling, is not sufficient to correct hepatic steatosis." (PMID 37520312, 2023).
type 2 diabetes (10 papers, 2011 to 2025). "Conclusively, the impact of insulin on GHR has been inconsistently reported, although the studies collectively show that deregulated insulin, high (e.g., type II diabetes) or low (malnutrition), negatively impacts hepatic GHR levels." (PMID 28486400, 2017). "In this review, we have discussed the differences in tissue proteomic profiles between 3 commonly studied mouse models of type 2 diabetes and aging: bGH, GHR−/− and C57BL/6J mice on HFD." (PMID 28670222, 2017).
gastric cancer (9 papers, 2012 to 2025). A primary or metastatic malignant neoplasm involving the stomach. "Our results revealed that GHR silence decreased gastric cancer cell growth; however, the cause of this reduction is unclear." (PMID 33492754, 2021). "In this study, a reduction in the phosphorylation of PI3K and AKT pointed that GHR deficiency inhibited the PI3K/AKT signalling pathway in gastric cancer cells." (PMID 33492754, 2021). "We found that GHR was highly expressed in gastric cancer cell lines, and inhibiting its expression caused cell growth suppression and cell apoptosis increase during G1‐S transition." (PMID 33492754, 2021). "Flow cytometry showed that GHR knockout significantly stimulated gastric cancer cell apoptosis compared with control group, which was also verified by Western blot that GHR deficiency induced the protein level of cleaved‐PARP, a valuable marker of apoptosis." (PMID 33492754, 2021). "GHR deficiency inhibited gastric cancer cell growth and induced cell apoptosis, further blocking cell cycle progression from G1 to S phase." (PMID 33492754, 2021). "In order to evaluate the mechanism underlying the role of GHR in gastric cancer progression, this study examined the association between GHR and PI3K/AKT signalling pathway." (PMID 33492754, 2021). "Flow cytometry showed that GHR knockout significantly stimulated gastric cancer cell apoptosis and caused G1 cell cycle arrest, which was also verified by Western blot that GHR deficiency induced the protein level of cleaved‐PARP, a valuable marker of apoptosis." (PMID 33492754, 2021). "Furthermore, we also investigated the mechanism underlying the association between GHR and gastric cancer." (PMID 33492754, 2021). "GHR has direct interaction with the m6A protein demonstrated by the m6A RIP-qRT-PCR experiment in gastric cancer cell lines." (PMID 40344709, 2025). "The protein levels of p-PI3K and p-AKT are decreased after knocking down GHR in gastric cancer cell lines." (PMID 37337300, 2023). "Knockdown of GHR significantly stimulated apoptosis in gastric cancer cells, and resulted in arrest of the G1 cell cycle." (PMID 35909123, 2022). "Flow cytometry showed that GHR knockout significantly stimulated gastric cancer cell apoptosis compared with control group." (PMID 33492754, 2021). "So far, little studies comprehensively and systematically detect the roles of GHR in gastric cancer." (PMID 33492754, 2021). "On the basis of the results, that GHR regulates gastric cancer cell growth and apoptosis through controlling G1 cell cycle progression via mediating PI3K/AKT signalling pathway." (PMID 33492754, 2021). "In the present study, we provide a novel understanding for GHR in gastric cancer that GHR regulates gastric cancer cell growth and apoptosis through controlling G1 cell cycle progression via mediating PI3K/AKT signalling pathway." (PMID 33492754, 2021). "Mouse xenograft model of human gastric cancer cell, which was transfected with siGHR showed the same result that silencing the expression of GHR in cell inhibited tumour development and growth." (PMID 33492754, 2021). "Total 11 tumour tissues and 11 normal mucosa samples from gastric cancer patients were used to detect the expression level of GHR." (PMID 33492754, 2021). "It showed that the MKN-45 cell line is a human gastric carcinoma cell line in which GHR is negatively expressed." (PMID 30673747, 2019). "Immunohistochemical analysis revealed that the percentage of positive GHR expression in human gastric cancer was 75% (36/48), and RT-PCR revealed that the percentage of positive GHR expression was 56.25% (27/48)." (PMID 23554765, 2012). "In conclusion, our study, which provided evidence of GHR expression and upregulation in human gastric cancer, indicated a role for GHR signaling in human gastric cancer." (PMID 23554765, 2012). "In this study, the results clearly demonstrated that GHR was expressed in human primary gastric cancer." (PMID 23554765, 2012).
gastric cancer (continued). "We showed that increased GHR productions were observed in gastric cancer cells compared with normal cells, suggesting GHR expression might play a role in gastric cancer development." (PMID 33492754, 2021). "Therefore, to fill the gap, this study addressed the influences of GHR expression on cell growth and apoptosis of gastric cancer cell lines as well as tumour growth of mice model." (PMID 33492754, 2021). "Our study focused on the possible relationship between gastric cancer and GHR." (PMID 33492754, 2021). "In addition, GHR has been reported to be involved in various types of cancer in recent years, including gastric cancer." (PMID 33492754, 2021). "In our study, GHR was highly expressed in gastric cancer tissues and cell lines." (PMID 33492754, 2021). "The protein level of GHR in gastric cancer cell was assessed by western blot." (PMID 33492754, 2021). "Thus, we detected the impact of GHR inhibition on gastric cancer cell cycle progression by cytofluorimetry." (PMID 33492754, 2021). "In contrast, GH antagonists might be used in gastric cancer showing positive GHR expression in the future." (PMID 23554765, 2012). "This study indicates that GH and GHR play a role in human primary gastric cancer, but the exact mechanism involved remains unclear." (PMID 23554765, 2012). "However, the roles of GHR in gastric cancer are still unclear." (PMID 33492754, 2021). "Thus, we further investigated the effects of GHR on gastric cancer cell growth and apoptosis." (PMID 33492754, 2021). "However, GHR expression in primary gastric cancer has been rarely reported." (PMID 23554765, 2012). "Studies related to gastric cancer have shown that GHR regulated the G1 cell cycle progression by mediating the PI3K/AKT signaling pathway, thereby regulating the growth and apoptosis of gastric cancer cells." (PMID 35909123, 2022). "Our data showed that GHR silence inhibited the protein levels of p‐PI3K and p‐AKT in both SGC‐7901 and MGC‐803 cells, suggesting GHR was involved in gastric cancer by regulating PI3K/AKT signalling pathway." (PMID 33492754, 2021). "However, the underlying mechanism of GHR in gastric cancer has not been defined." (PMID 33492754, 2021). "Our data suggest that GHR regulates gastric cancer cell growth and apoptosis through controlling G1 cell cycle progression via mediating PI3K/AKT signalling pathway, which provides a novel understanding for the role of GHR in gastric cancer." (PMID 33492754, 2021).
Hypoglycemia (9 papers, 2008 to 2025). A decreased concentration of glucose in the blood. "This study investigates the pathophysiology of juvenile hypoglycemia in a large animal model for GH receptor (GHR) deficiency (the GHR-KO pig) and elucidates mechanisms underlying the transition to normoglycemia in adulthood." (PMID 41125144, 2025). "In accordance with this idea, GH or GH receptor (GHR) deficiency increases the risk of hypoglycemia." (PMID 34576072, 2021). "A characteristic consequence of GHR deficiency in humans is juvenile hypoglycemia, but glucose levels normalize when the patients become adults." (PMID 32277923, 2020). "Another interesting topic are age-related changes in the function of the GH/GHR system, in particular the question of why GHR deficiency leads to juvenile hypoglycemia that normalizes during puberty." (PMID 32277923, 2020). "Reduced insulin secretion is another counterregulatory mechanism to avoid hypoglycemia in adult GHR-KO pigs." (PMID 41125144, 2025). "Our study identified increased insulin sensitivity as the major driver of juvenile hypoglycemia in GHR-KO pigs." (PMID 41125144, 2025). "Since we also wanted to study the effects of hypoglycemia, which occurs transiently in juvenile but disappears in adult GHR-KO pigs, we decided to study lymphocyte proliferation in 3-month-old animals." (PMID 37189345, 2023). "We have already detected differences in mitochondrial respiration in immune cells of hyperglycemic pigs expressing mutant insulin C94Y (INSC94Y) which makes it interesting to study the effects of prolonged hypoglycemia in GHR-KO pigs on immunometabolism." (PMID 37189345, 2023). "A GHR-knockout (GHR-KO) pig was developed as a model for LS, which displays many of the same features as humans with LS-like transient juvenile hypoglycemia." (PMID 37189345, 2023). "•GHR-deficient pigs show markedly reduced serum IGF1 and IGFBP3 levels, and transient juvenile hypoglycemia." (PMID 29678421, 2018). "GHR-KO pigs had a markedly increased percentage of total body fat relative to body weight and displayed transient juvenile hypoglycemia along with decreased serum triglyceride and cholesterol levels." (PMID 29678421, 2018). "In contrast to previous reports, we found GHR-KO mice on CR to beless responsive than theirad libitum (A.L.)counterparts to the hypoglycemia-inducing effects of insulin." (PMID 25789159, 2014). "Moreover, in the context of hypoglycemia observed in Mir137−/−, the expression level of Slc2a4 (Glut4), a glucose transporter involved in carbohydrate metabolism and modulated by GH/GHR signaling, was also reduced." (PMID 40598150, 2025). "Hypoglycemia in GHR-KO pigs might force immune cells to turn to substrates other than glucose (such as amino acids) to meet their energy needs." (PMID 37189345, 2023). "Similarly, young (3 months old) GHR-KO pigs showed fasting hypoglycemia, whereas normal glucose levels were measured at age 6 months." (PMID 32277923, 2020). "GHR-KO pigs showed juvenile hypoglycemia that normalized when the animals reached sexual maturity." (PMID 29678421, 2018). "Moreover, GHR-KO pigs display transient juvenile hypoglycemia." (PMID 37189345, 2023). "Thus, hypoglycemia in GHR-KO pigs might contribute to the reduced IFI44 protein abundance in CD4− PBMCs." (PMID 37189345, 2023). "Thus, we hypothesized that prolonged hypoglycemia and enhanced insulin sensitivity in GHR-KO pigs may lead to enhanced immune function, especially in CD4+ T cells." (PMID 37189345, 2023). "Similarly, central GHR signaling potentially regulates food intake, energy expenditure, body adiposity and glucose homeostasis, particularly in certain situations, like food deprivation, pregnancy and after hypoglycemia." (PMID 34576072, 2021). "Despite hypoglycemia and ketosis, young GHR-KO pigs showed no increase in NEFA levels, which were in fact slightly decreased in comparison with young controls (0.70 ± 0.07 vs. 0.80 ± 0.08 mmol/L; p = 0.2174)." (PMID 41125144, 2025).